TNF (tumor necrosis factor)
Diseases named in the same sentence as TNF in open-access papers (continued):
Sharing a sentence is not in itself a finding about the gene and the disease.
rheumatoid arthritis (continued). "Previous studies have reported a correlation between increases in the expression of TNF-α, resistin, and visfatin in a variety of inflammatory diseases including rheumatoid arthritis, inflammatory bowel disease, and psoriasis." (PMID 28018676, 2016). "The TNF-α level is increased in numerous inflammatory diseases, such as rheumatoid arthritis, inflammatory bowel disease, psoriasis, chronic obstructive pulmonary disease, and asthma." (PMID 26783416, 2016). "TLR4 and inflammasome pathways are implicated in the pathogenesis of autoimmune diseases such as rheumatoid arthritis, and TNFα blockade specifically alters these responses by its effect on NFkB, playing a key role in NLRP3 priming." (PMID 27965661, 2016). "Anti-Tumor Necrosis Factor (TNF) drug therapies were first introduced in rheumatoid arthritis (RA) treatment more than 10 years ago." (PMID 27549132, 2016). "During septic shock increased TNF levels were found to be accompanied by a significant decline in total serum cholesterol, whilst TNF inhibitor treatment was associated with increased levels of HDL and total cholesterol in rheumatoid arthritis patients." (PMID 26248682, 2016). "For example, evidence suggests that rheumatoid arthritis patients with TLOs in inflamed joint tissues display an inferior response to frontline biological therapies that target TNF." (PMID 27752256, 2016). "In rheumatoid arthritis, macrophages infiltrate the synovial membrane and produce IL-1, IL-6, TNF-α, and other inflammatory cytokines." (PMID 27609223, 2016). "The importance of TNF-alpha in protection against Mtb is highlighted by reactivation of latent infection in people (such as rheumatoid arthritis patients), who have been treated with anti-TNF agents." (PMID 27709522, 2016). "The success of TNFα mAb agents in the clinical treatment of rheumatoid arthritis and ankylosing spondylitis are excellent examples of this." (PMID 27562139, 2016). "TNF receptor levels also correlate with disease activity for inflammatory bowel disease patients, and in rheumatoid arthritis TNF-α levels are increased in the synovial fluid of affected joints and serum sTNFR1 levels are also elevated." (PMID 26925234, 2016). "The OR (95%CI) for therapy persistence was 1.50 (1.34-1.67) for the anti-TNF (+/-DMARD) group as compared with the DMARD group in the first year for the patients with rheumatoid arthritis, and 2.33 (1.74-3.11) for the patients with ankylosing spondylitis." (PMID 27556964, 2016). "TNF-α has a critical role in pathogenesis of chronic inflammatory diseases, such as rheumatoid arthritis and local inflammation." (PMID 27861614, 2016). "IL-1 is certainly a cytokine that has been implicated in the pathogenesis of rheumatoid arthritis, and targeting the IL-1 pathway via IL1RA (anakinra) has been used as an alternative biological treatment in patients failing therapy on TNFα blockade." (PMID 27579026, 2016). "Anti-TNF-α agents have been approved for therapeutic use across a range of inflammatory disorders, including Crohn’s disease, rheumatoid arthritis, spondyloarthritis and psoriasis." (PMID 28005985, 2016). "The tumor necrosis factor alpha (TNF) antagonists target a cytokine that regulates inflammation in multiple diseases, including rheumatoid arthritis (RA)." (PMID 27930739, 2016). "The TNF-α biological inhibitors have significantly improved the clinical outcomes of many autoimmune diseases, in particular rheumatoid arthritis." (PMID 27658047, 2016). "Other cytokines also interfere with hepcidin regulation: Inhibition of the tumor necrosis factor α (TNF-α) in patients with rheumatoid arthritis and AI led to a decrease of hepcidin levels." (PMID 27404499, 2016). "TNF-α is classically regarded as a proinflammatory cytokine, playing an important role in the pathophysiology of inflammatory diseases, such as rheumatoid arthritis and inflammatory bowel disease." (PMID 27747245, 2016).
rheumatoid arthritis (continued). "Recognized as a pro-inflammatory molecule and an autoantigen associated with rheumatoid arthritis, FSTL1 secretion results in upregulation of interleukin 1β (IL-1β), tumor necrosis factor α (TNF-α), and IL-6 in macrophages and fibroblasts." (PMID 26918942, 2016). "In a TNFα-rich environment, such as in the case of rheumatoid arthritis, we found that anti-TNF therapy prevents the TNFα-induced loss of CD28 on the residual CD28+ CD8+ and CD4+ T cells, but the numbers of CD28null T cells remain the same." (PMID 27933066, 2016). "Anti-Tumor Necrosis Factor (TNF) therapies are able to control rheumatoid arthritis (RA) disease activity and limit structural damage." (PMID 27549132, 2016). "We observed higher persistence rates for anti-TNF drugs (+/-DMARD) in patients with ankylosing spondylitis as compared to rheumatoid arthritis; and a higher persistence for DMARD in patients with rheumatoid arthritis as compared to ankylosing spondylitis." (PMID 27556964, 2016). "Tumor necrosis factor inhibitor (TNFi) therapy represents an important breakthrough in the treatment of the chronic inflammatory joint disease rheumatoid arthritis (RA)." (PMID 27912794, 2016). "Conversely, recent studies in platelets from rheumatoid arthritis have shown proinflammatory effects of TNF-α signalling via TNFR2, specifically upregulation of the adhesion molecule P-selectin leading to platelet-neutrophil complex formation." (PMID 27747245, 2016). "Based on a previous report, several transgenic mouse lines were established in the past 30 years by over-expressing human TNF-α, and developed an erosive polyarthritis, these models exhibited many characteristics observed in rheumatoid arthritis patients." (PMID 26977076, 2016). "The greatest advancement in good prognosis of rheumatoid arthritis over the last decade has been made due to the identification of the pivotal role of TNF-α in its pathogenesis." (PMID 27467817, 2016). "Patients with autoimmune conditions, such as rheumatoid arthritis, spondyloarthritis, and Crohn’s disease, and treated with anti-TNF-α agents have benefited from concomitant methotrexate treatment." (PMID 26870037, 2016). "For example, in rheumatoid arthritis TNF‐α plays a central role in pathology and neutrophil function is activated in the blood of untreated patients." (PMID 27042300, 2016). "In rheumatoid arthritis, prediction of response to TNF-alpha inhibitor (TNFi) treatment would be of clinical value." (PMID 27558398, 2016). "All data was collected and summarized with regard to adverse effects including pregnancies with rheumatoid arthritis patients treated with anti-TNF." (PMID 28044081, 2016). "Since the early 1990s, TNFα has become a validated therapeutic target for the treatment of several autoimmune disorders including rheumatoid arthritis." (PMID 26977076, 2016). "Previous studies have indicated that neutralization of TNF during rheumatoid arthritis treatment elicited a significant population of Tregs." (PMID 27995986, 2016). "In the same vein, experts recommend using other biologics with lesser risk of tuberculosis such as ustekinumab for psoriatic arthritis or rituximab for rheumatoid arthritis after tuberculosis treatment instead of TNF inhibitor reinitiating." (PMID 27101309, 2016). "Recently, our group reported that GV1001 decreased the production of TNF-α, IL-1β, and IL-6 in peripheral blood mononuclear cells from rheumatoid arthritis patients through the suppression of p38 MAPK and NF-κB activation." (PMID 27655706, 2016). "The plasma levels of TNFα are augmented in some pathologies, such as cancer, atherosclerosis, rheumatoid arthritis, and preeclampsia." (PMID 26824050, 2016). "In clinical practice, approximately one-third of patients with rheumatoid arthritis (RA) respond insufficiently to TNF-α inhibitors (TNFis)." (PMID 27631111, 2016).
rheumatoid arthritis (continued). "The TNF-α system is also strongly involved in inflammatory disorders such as inflammatory bowel disease and rheumatoid arthritis." (PMID 26925234, 2016). "Tumor necrosis factor is a therapeutic target in several diseases and anti-TNF treatment is successfully applied in rheumatoid arthritis, psoriasis, ankylosing spondylitis, and IBD." (PMID 27148273, 2016). "TNF-α is one of the key pro-inflammatory mediators involved in the pathogenesis of psoriasis, atopic dermatitis and rheumatoid arthritis and is often found in high amounts around psoriasis skin lesions." (PMID 27415000, 2016). "Anti TNF drugs have been widely used in rheumatoid arthritis (RA) but only 70 to 80 % of patients respond to this therapy." (PMID 26932562, 2016). "Anti-TNF agents have revolutionised rheumatoid arthritis (RA) treatment; however, a third of patients fail to achieve therapeutic responses." (PMID 28010726, 2016). "Inhibition of TNF-α activity has been successfully used to treat inflammatory diseases, like rheumatoid arthritis (RA), Crohn’s disease, and psoriasis." (PMID 27822210, 2016). "For instance, antibodies against TNFα are used for the treatment of rheumatoid arthritis, Crohn’s disease, and psoriasis." (PMID 26840958, 2016). "The sustained anti-TNF-α antibody response is beneficial to treatment of rheumatoid arthritis as excessive TNF-α is persistently expressed in patients." (PMID 27658047, 2016). "Studies using up-to-date medical techniques such as flow mediated dilation and laser Doppler perfusion imaging has demonstrated improved endothelial dysfunction in rheumatoid arthritis patients upon TNF-α blocker therapy." (PMID 27467817, 2016). "Further work is now necessary to determine if this transcriptional re‐programming occurs in vivo in human diseases driven by TNF‐α (e.g. rheumatoid arthritis)." (PMID 27042300, 2016). "For example, anti-TNF therapeutics have already been proven to be effective in fighting rheumatoid arthritis, a chronic inflammatory bone disease characterized by bone damage and elevated osteoclastic bone resorption around the affected joints." (PMID 27756280, 2016). "Tumor necrosis factor alpha is one of the main trigger of chronic inflammation in rheumatoid arthritis." (PMID 26977076, 2016). "IL-17A and TNF exert a synergistic effect in FLS in rheumatoid arthritis by increasing the secretion of many factors, including IL-6, IL-8 and granulocyte-colony stimulating factor (G-CSF)." (PMID 27165410, 2016). "MEK-162 (Array BioPharma Inc.)is a selective non-ATP-competitive MEK inhibitor initially developed as an anti-rheumatoid arthritis drug due to its profound inhibitory effects on the NF-κB pathway leading to decreased IL-1, IL-6 and TNF activities." (PMID 27708250, 2016). "In Germany, the clinical use of TNF-α inhibitors in the therapy of rheumatoid arthritis (RA) grew from 2 % of treated patients in 2000 to 20 % in 2008." (PMID 27080399, 2016). "Golimumab is a human monoclonal antibody that also targets the TNF and it is currently used to treat moderate to severe active psoriatic arthritis, rheumatoid arthritis, and ankylosing spondylitis." (PMID 28044081, 2016). "For instance, EVs derived from synovial fluid of patients with rheumatoid arthritis (RA) have higher levels of TNF-alpha compared to healthy controls." (PMID 27597941, 2016). "Neutrophils exposed to chronic inflammatory stimulants like TNFα and IL-1β, such as occurs in rheumatoid arthritis, have altered function." (PMID 26928196, 2016). "It has been determined that the cPLA2-α gene is regulated by p42/p44 MAPK in response to stimulation by TNF-α and IL-1β in tracheal smooth-muscle cells or rheumatoid arthritis fibroblasts." (PMID 26593914, 2015). "For example, anti-human tumor necrosis factor (TNF) alpha-specific monoclonal antibody or anti-human CD20-specific monoclonal antibody has been extensively used as an innovative medicine for patients with rheumatoid arthritis or leukemia." (PMID 26163364, 2015).
rheumatoid arthritis (continued). "Benefits related to TNF-α blockade have already been demonstrated in other pathological conditions, such as acute shocks, rheumatoid arthritis, systemic vasculitis, idiopathic dilated cardiomyopathy and type-1 diabetes mellitus." (PMID 26237421, 2015). "Tumor necrosis factor (TNF) inhibitors represent an important advance in therapy for rheumatoid arthritis (RA)." (PMID 25648415, 2015). "Conversely, a study using synovium-derived MSCs from rheumatoid arthritis patients showed that IL-17, as well as TNF-α, alone and in combination, stimulated proliferation of synovial T cells in the presence of these mesenchymal cells." (PMID 25999667, 2015). "Rheumatoid arthritis patients are being treated successfully with anti-TNFα agents for many years now." (PMID 26270565, 2015). "Anti-TNF is currently being used to treat human inflammatory and autoimmune diseases, for example, rheumatoid arthritis." (PMID 26121276, 2015). "We report four cases of successful treatment with certolizumab pegol (CZP) of rheumatoid arthritis (RA) patients with persistent inflamed residual mono- or oligosynovitis resistant to prior TNF-α inhibitors." (PMID 26451269, 2015). "In patients with rheumatoid arthritis, TNF-α is found in the synovial liquid contributing to joint inflammation." (PMID 26312490, 2015). "Biological agents inhibiting TNF-α and other molecules involved in inflammatory cascade have been increasingly used to treat rheumatoid arthritis (RA)." (PMID 26496968, 2015). "Tumor necrosis factor-alpha inhibitors are widely used agents in the treatment of immune disorders such as rheumatoid arthritis and inflammatory bowel disease." (PMID 26044064, 2015). "TNF-α, a major chronic inflammatory cytokine, was shown to induce rheumatoid arthritis, osteoporosis, periodontal disease, and implantation failures." (PMID 26516841, 2015). "The NF-κB pathway is induced by a wide variety of stimuli, including cytokines such as the tumor necrosis factor-alpha and interleukin-1β, both of which are the targets of biologic therapies used to treat rheumatoid arthritis and juvenile idiopathic arthritis." (PMID 26310571, 2015). "In autoimmune disease TNF α is the main target for monoclonal antibodies (e.g., rheumatoid arthritis)." (PMID 26357658, 2015). "The introduction of tumor necrosis factor-alpha (TNF-α) antagonists has substantially improved patient’s clinical outcome in rheumatoid arthritis (RA)." (PMID 25884688, 2015). "We investigated the production of tumor necrosis factor alpha (TNFα), as the main regulator of other inflammatory cytokines in the synovial membrane, inhibition of which can pose as a powerful treatment for rheumatoid arthritis." (PMID 25977699, 2015). "And some groups identified FSTL1 as a new proinflammatory mediator that contributes to rheumatoid arthritis by promoting the expression of TNFα, IL-1β, IL-6 and IL-8, as well as by enhancing the interferon-γ (IFN-γ) signaling pathway in a mouse model." (PMID 25888873, 2015). "Biologic disease-modifying antirheumatic drugs (bio-DMARDs), especially in the form of TNF-α inhibitors (TNFi), are established treatment options for patients with a wide variety of immunoinflammatory rheumatic diseases, including rheumatoid arthritis (RA)." (PMID 25759761, 2015). "For example, in a study of rheumatoid arthritis, Derinat was found to suppress tumor necrosis factor alpha (TNF-α) and accelerate lymphocyte blast transformation in rats." (PMID 26569211, 2015). "The objective of this retrospective cohort study was to determine the effect of tumor necrosis factor inhibitor (TNFi) therapy on the risk of head and neck cancer (HNC) recurrence or HNC-attributable death in patients with rheumatoid arthritis (RA)." (PMID 26599370, 2015). "Autoimmune diseases like rheumatoid arthritis and inflammatorybowel disease are treated with TNF-alpha-blocking antibodies such as infliximab and adalimumab." (PMID 26511203, 2015).
rheumatoid arthritis (continued). "Recent clinical data, obtained with either chimeric TNF-α antibodies or soluble TNF-α receptor in the treatment of rheumatoid arthritis and Crohn’s disease, have confirmed the key role of TNF-α in these inflammatory disorders." (PMID 26307982, 2015). "Dysregulation of TNF-α results in the onset of diseases such as rheumatoid arthritis (RA), inflammatory bowel disease (IBD), Alzheimer's disease, and some cancers." (PMID 26516703, 2015). "On the other hand, anti-TNF-α medicine had therapeutic effect on ameliorating both inflammation and joint damage in rheumatoid arthritis patient." (PMID 25861246, 2015). "Within the last decade the field of therapeutics have witnessed an evolution in the treatment armamentarium of rheumatoid arthritis with the lead of the Tumor necrosis factor inhibitors (TNF-I) as the first line biologic drugs." (PMID 25977895, 2015). "It has been shown that both cigarette smoke condensate (CSC) and polycyclic aromatic hydrocarbons (PAHs) are able to induce interleukin-1 (IL-1β) and tumor necrosis factor α (TNFα) at mRNA and protein levels in the rheumatoid arthritis cells." (PMID 25561937, 2015). "Mechanistically, ciclamilast inhibited an increase in the expression level of IL-1β, IL-6, and TNF-α, leading to potential effects on both the acute and chronic phases in the treatment of rheumatoid arthritis." (PMID 26000303, 2015). "Elevated levels of TNF-α have been reported in rheumatoid arthritis, ankylosing spondylitis, irritable bowel disease, and psoriasis." (PMID 26236424, 2015). "Although the link between TNF-α and bone marrow suppression in anemia of chronic disease such as rheumatoid arthritis is well documented, the inadequate response of the bone marrow during severe malarial anemia can be attributed to factors other than TNF-α." (PMID 25781011, 2015). "Its relevance to disease is well established and treatment with TNF-α antagonists has been highly efficacious in a range of inflammatory disorders, e.g. rheumatoid arthritis." (PMID 26352810, 2015). "Etanercept (ETN) is a completely human fusion TNF-soluble receptor that inhibits the effect of the proinflammatory cytokine TNF-α, which has an important role in synovitis and joint damage in rheumatoid arthritis (RA)." (PMID 26665003, 2015). "Anti-tumor necrosis factor (TNF)-α therapy such as infliximab for rheumatoid arthritis (RA) is used not only to inhibit inflammation, but also to suppress bone and joint destruction." (PMID 26543742, 2015). "TNF-α is a potent proinflammatory cytokine detected in high concentrations in the synovial cavity of patients with rheumatoid arthritis." (PMID 25878716, 2015). "Tumour Necrosis Factor-α (TNF-α) inhibition has been transformational in the treatment of patients with inflammatory disease, e.g. rheumatoid arthritis." (PMID 26352810, 2015). "Furthermore, the upregulation of ADAMTS-7 was also associated with the increased level of TNF-α in rheumatoid arthritis (RA) patients and patients with femoral neck fracture (FNF) and osteonecrosis of femoral head (ONFH) at different stages." (PMID 26696755, 2015). "For example, TNF-neutralizing antibodies are approved and widely used for the treatment of various inflammatory diseases including rheumatoid arthritis, psoriatic arthritis, and Crohn’s disease." (PMID 26694384, 2015). "A selective search and evaluation of the literature was performed with regard to the mode of action of TNF inhibitors, tocilizumab and methotrexate in rheumatoid arthritis." (PMID 25604317, 2015). "Rheumatoid arthritis is an autoimmune arthritis in which two inflammatory cytokines, tumor necrosis factor-α and interleukin-1β, play a critical role in the induction and progression of the disease." (PMID 26033326, 2015). "Anti-TNF-α agents are used to treat various chronic inflammatory diseases (rheumatoid arthritis, spondyloarthropathies, psoriasis, and Crohn’s disease)." (PMID 26425632, 2015).